ALK (ALK receptor tyrosine kinase)
Diseases named in the same sentence as ALK in open-access papers (continued):
Sharing a sentence is not in itself a finding about the gene and the disease.
tumor (continued). "Our previous study suggested that serum tumor markers (STMs) integrated with other clinical factors could be a valuable noninvasive tool for predicting EGFR mutations and ALK positivity in NSCLC patients." (PMID 35624472, 2022). "To determine mechanisms of ALK inhibitor resistance, we first screened preclinical models and subsequently analyzed tumor samples or liquid biopsies obtained from patients before and during ALK inhibitor treatment (before/after initial response and during disease progression)." (PMID 35689207, 2022). "For example, the reported association of TFCP2 fusion positive SCS-RMS with ALK overexpression might suggest a role for ALK inhibitors, although the potential benefits of ALK inhibition in this tumor type need to be further addressed." (PMID 36551545, 2022). "The data indicate that cfDNA analysis detected ALK p.R1275Q-mutated tumor clones or subclones that were not reflected in the tumor biopsy used to characterize molecular disease." (PMID 35565208, 2022). "Finally, as a proof of concept, the efficacy of ALK inhibition was demonstrated in both patient-derived organoids and in tumor xenografts in vivo." (PMID 35351152, 2022). "Finally, a comprehensive imaging analysis of the 3D tumor growth, revealed a functional role for ALK in the formation of the tumor bulk in CMS1." (PMID 35351152, 2022). "At that conference, some participants pointed out the possibility of the tumor being ALK-RCC." (PMID 35718773, 2022). "Twenty-four hours after administration, APG-2449 exerted dose-dependent suppression of tumor phosphorylated ALK (p-ALK), Ak strain transforming (p-AKT), extracellular signal-regulated kinase (p-ERK1/2), and signal transducer and activator of transcription (p-STAT3)." (PMID 35820889, 2022). "Molecular tumor tissue analysis detected neither MYCN nor ALK copy-number alterations nor ALK hotspot mutations." (PMID 35565208, 2022). "Hence, this topic will be the focus of future research in the field of ALK-altered tumor immunotherapy." (PMID 35958559, 2022). "In this tumour, with the histological subtype of adenocarcinoma, an additional translocation in the anaplastic lymphoma kinase (ALK) could be monitored by FISH analysis, the only one in the Rn-exposed cohort (1/17; 6%)." (PMID 36291897, 2022). "The study revealed that patients with EGFR or ALK tumor mutations did not benefit from chemotherapy plus atezolizumab compared with chemotherapy alone." (PMID 36426286, 2022). "Immunohistochemistry (IHC) showed tumor cells are positive for vimentin, ALK, BCL2, and SMA." (PMID 36304484, 2022). "In cases of central nervous system (CNS) metastases in NSCLC (brain or leptomeningeal), plasma ctDNA genotyping is constrained by a blood-tumor barrier, and thus alternative sources of ctDNA, such as cerebrospinal fluid, can yield a higher source of ctDNA for the detection of ALK rearrangements." (PMID 36139444, 2022). "ALK and ROS1 kinases demonstrate significant similarities with regard to amino acid sequence, mode of genetic alterations, the spectrum of associated tumor types, correlations with clinical characteristics of cancer disease, and patterns of sensitivity to tyrosine kinase inhibitors." (PMID 35322575, 2022). "ctDNA is defined as tumor tissue-specific DNA fragment released in the bloodstream and its level is correlated with tumor progression, being the most frequent biomarker used in ALK-positive NSCLC resistance monitoring." (PMID 34082691, 2022). "However, previous studies have shown that tumor response to ALK inhibitors is heterogeneous in patients with ALK-positive NSCLC." (PMID 36042596, 2022). "First, gene fusions are considered strong oncogenic drivers and recent clinical data show strong efficacy of compounds targeting, e.g., neuregulin 1 (NRG1), neurotrophic tyrosine kinase receptor (NTRK) or anaplastic lymphoma kinase (ALK) fusions in patients across various tumor types." (PMID 36231142, 2022).
tumor (continued). "The total number of circRNA species but not expression abundance was higher in plasma from male patients and in tumor tissue from non-smokers and ALK mutations carriers (plasma and tissue) than in their according counterpart." (PMID 35123506, 2022). "Globally, there have been additional efforts to target either ALK or ROS1 in rare tumor types." (PMID 35233056, 2022). "This suggests that ALK mutant NSCLC may facilitate cancer initiation by enabling tumor evasion of the immune system through downregulation of HLA expression." (PMID 36591504, 2022). "In this situation, even complete inhibition of ALK cannot prevent tumor progression, and combination therapy or targeting of proteins other than ALK (eg, CD30, B7-H3, heat shock protein [HSP]90, etc) may be necessary." (PMID 35211406, 2022). "Immunohistochemistry revealed that the tumor was positive for ALK." (PMID 36626420, 2022). "However, an additional IHC analysis revealed that the tumor cells were diffusely positive for ALK-IHC." (PMID 35718773, 2022). "Moreover, in another small study, it was also shown that CTCs recapitulate the ALK rearrangement status of tumor tissue, and, therefore, CTCs represent a suitable alternative to tissue biopsy for guiding treatment." (PMID 36139444, 2022). "We also put into context the utility of tumour-derived exosomes and cfDNA for detecting crucial alterations to ALK and MYCN genes in NB patient primary and relapse samples, while comparative studies of the diagnostic accuracy of tumour-derived exosomes and cfDNA are still largely lacking." (PMID 36362869, 2022). "Out of a total of 372 cases, we identified one tumor with robust ALK staining." (PMID 36337169, 2022). "Importantly, p-ALK expression is associated with resistance to PARPi and positively correlated with p-Y19-CDK9 expression in the human tumor tissues." (PMID 36284291, 2022). "In this case, combination with an EGFR inhibitor restored sensitivity to alectinib and promoted tumour regression in alectinib-resistant mouse models suggesting that resistance was mediated not by ALK mutations, but rather by upregulation of bypass pathways." (PMID 35884511, 2022). "Furthermore, in the “precision medicine” era where tumor-agnostic therapies represent a new revolutionary approach to cancer treatment, ALK-i are earning a potential role in the agnostic-setting of ALK-positive tumors." (PMID 35409355, 2022). "This suggests that in the context of neuronal/neuroendocrine lineage differentiation, ALK expression could be a particularly relevant contributor to tumor progression." (PMID 36337169, 2022). "Furthermore, alectinib, a novel ALK inhibitor, significantly reduced tumor cell growth in a neuroendocrine ALK F1174C-expressing PCa model." (PMID 36359354, 2022). "This is particularly important as inhibition of alternative tumor-promoting pathways in combination with ALK inhibition might prevent the development of drug resistance." (PMID 36045346, 2022). "The tumor-specific DNA markers including point mutations in EGFR or BRAF genes, rearrangements involving ALK or ROS1 genes and fusions of NTRK1/2/3 genes along with tumor mutation burden (TMB) and PDL-1 RNA expression serve as guides in proper therapy selection." (PMID 35837614, 2022). "However, CAR-T therapy with respect to ALK rearranged cancers requires further analysis, and this class of tumor cell surface should only be partially a target of CAR-T." (PMID 36591504, 2022). "Indeed, in preclinical studies, it has been shown that crizotinib elicits beneficial effects in combination with radiotherapy in ALK-positive NSCLC cell lines by reducing tumor proliferation, microvascular density and perfusion." (PMID 35158987, 2022). "Through the widespread use of NGS, an increasing number of tumor types has been shown to harbor ALK alterations, suggesting that ALK-directed therapies could be of used outside of its current established indications." (PMID 36337169, 2022).
tumor (continued). "Interestingly, we found increasing ALK tumor expression to be an independent indicator of progressively shorter DFI by multivariate analysis, suggesting strong ALK expression to be associated with a more aggressive clinical course." (PMID 35551625, 2022). "However, CAR functionality is regulated by target antigen and CAR density, and low expression of either contributes to the limited anti-tumor efficacy of ALK CAR-T." (PMID 35958559, 2022). "The European Organization for Research and Treatment of Cancer (EORTC) “CREATE” trial was designed as a multi-center multi-tumor trial to evaluate crizotinib in a range of cancer types known to harbor alterations in the targets of crizotinib (ALK, MET, and ROS-1)." (PMID 36034555, 2022). "Data obtained from H&E and immunohistochemical (IHC) staining indicated that XMU‐MP‐5 dose‐dependently inhibited ALK activity and induced tumor cell apoptosis in vivo, as indicated by the decreased ALK phosphorylation level and the induction of caspase‐3 cleavage, respectively." (PMID 34845836, 2022). "Intratumoral and intertumoral heterogeneity including temporal heterogeneity from treatment selection pressure is expected with ALK, with acquired drug-resistant progressing sites of disease expected to harbor a unique genomic profile to the primary tumor and controlled sites of disease." (PMID 36003760, 2022). "Furthermore, ALK-resistance mutations and an EMT component can simultaneously co-exist in two different tumor cell subpopulations in patients with ALK-rearranged NSCLC who are resistant to crizotinib." (PMID 36551587, 2022). "Our findings suggest that feedback loops for HER3 reactivation via ZEB1 may contribute toward tumor differentiation in DT and reversible ALK-rearranged NSCLC cells and reveal a novel DT system with MET related to HER3 activation in cancer." (PMID 35042943, 2022). "However, logistics for obtaining repeat tumor biopsies are complicated and seldom feasible leading to an empirical prescription of sequential ALK‐Is." (PMID 34058070, 2021). "The patient was subsequently treated with alectinib but tumor progression was assessed 3.1 months later prompting a switch of treatment to lorlatinib, but that also failed after 1.8 months, suggesting that the tumor had primary resistance to ALK‐Is." (PMID 34058070, 2021). "In tumors with NPM1-ALK fusion, ALK protein may be detected in the nucleus and cytoplasm, while in RANBP2-ALK neoplasms, it shows nuclear membrane staining." (PMID 33237469, 2021). "When comparing the change in methylation per site, we observed that in ALKKO compared with Ctrl, most sites lost less than half of their methylation, whereas in ALK versus Ctrl we detected CpGs with particularly large changes reflecting stable tumor-specific changes in DNA methylation patterns." (PMID 33310759, 2021). "Tumor samples harboring EGFR or ALK alterations were respectively 127 (17.7 %) and 34 (13.9 %)." (PMID 34016641, 2021). "Thus, EMT and ALK-rearrangement are evidently independent mechanisms, co-occurring in ALK inhibitor-resistant tumor specimens." (PMID 33572278, 2021). "Further analysis of the DN population based on CD25 and CD44 expression revealed that in tumor-free thymi, most ALK+ cells were DN3 (CD25+CD44−) and DN4 (CD25−CD44−) stage thymocytes, which correlates with the developmental stages at which Cd4 driven NPM-ALK expression was induced." (PMID 33310759, 2021). "Thus, ALK appears as an ideal oncoantigen for potential tumor vaccination and the monitoring of NPM-ALK-specific immune responses during therapy will provide new insights into the interplay between ALCL and the immune system." (PMID 33466277, 2021). "ALK translocation was detected in 8.3% of tumor tissues but only 2.4% in CSF and 2.7% in plasma." (PMID 34671549, 2021). "If tumor cells are resistant to crizotinib, second generation ALK inhibitors such as ceritinib and brigatinib may be used." (PMID 37206935, 2021).
tumor (continued). "ALK mutation was found in 3 of 37 studied tumours (2 MNA and 1 non-MNA) and amplification in 2 out of 58 cases (both MNA)." (PMID 34680323, 2021). "Positivity for ALK and p-ALK was frequently detected in the same tumor samples (P < 0.001)." (PMID 34029351, 2021). "Keeping in mind the correlation of MCPyV positivity and expression of ALK and p-ALK, ALK phosphorylation may be facilitated by the virus or by some other unknown factor present in the cells or by the tumor microenvironment." (PMID 34029351, 2021). "Radiation-induced ALK activity in NSCLC-derived exosomes may be a key factor in promoting tumor progression and resistance to ALK inhibitors." (PMID 33628582, 2021). "ALK inhibitors such as crizotinib may be used in multifocal, refractory disease, and unresectable tumor." (PMID 37206935, 2021). "Since the amino acid sequence of the kinase domains of ROS1 and ALK are highly homologous, selective inhibitors of ALK, including crizotinib, have shown anti-tumor activity in vitro and have been explored clinically in the treatment of patients with ROS1-rearranged tumors." (PMID 34511132, 2021). "In comparison, ALK amplification leading to unrestricted expression of ALK during undefined developmental stages results in the severe disruption of specification and consequent tumour formation, or death during development, as seen in Sox10::CreERT2/+; LSL-ALKF1174L mice." (PMID 34769149, 2021). "Among the eight cases with positive ALK FISH (>20% tumor cells), IHC detected four positive cases." (PMID 34066104, 2021). "Interestingly, this resistance was labile and reversible after hypoxic reversion or HIF-1α inhibition, highlighting the potential relevance to counteract hypoxia in ALK-rearranged tumours harbouring TKI resistances." (PMID 34298636, 2021). "Second, regarding ALK tumor antigen presentation, one can hypothesize that autophagy may potentially participate in NPM-ALK epitope processing and delivery to MHC class I and II molecules." (PMID 34685497, 2021). "We hypothesize that the in vivo MCC tumor microenvironment could promote activation of ALK via an unknown mechanism." (PMID 34029351, 2021). "Because the tumor was retrieved from brain metastasis, false positivity could be explained by contaminated ALK mRNA transcripts from adult brain tissue." (PMID 34559836, 2021). "We therefore analyzed whether the distance between two neighboring CpGs had an influence on methylation changes of those CpGs in ALK tumor or knockout cells (ALK and ALKKO) relative to Ctrls." (PMID 33310759, 2021). "In summary, our findings suggest that the role of ALK and RET in NB tumor formation is complex; however, dual inhibition of these two RTKs may be beneficial in ALK-driven NB." (PMID 33921066, 2021). "Robust ALK FISH results may be difficult to achieve for small biopsy specimens containing less than 100 interpretable tumor cells." (PMID 34559836, 2021). "PD-1, a member of the CD28 family, is constitutively expressed on activated T cells, B cells, DCs, and macrophages, while PD-L1 is often expressed on tumor cells and upregulated due to the host cell immune response, loss of PTEN, and enhanced anaplastic lymphoma kinase (ALK) signaling." (PMID 34359588, 2021). "While we observed only mild synergy when combining ATR and ALK inhibition, we rationalised that combination with lorlatinib, which has previously been shown to reduce tumour growth in ALK-driven NB mouse models, may improve treatment responses." (PMID 34819497, 2021). "Immunohistochemistry (IHC) report was strongly positive for PD-L1 in 95% of the tumor cells, negative ALK gene rearrangement, and no EGFR mutation was detected." (PMID 33070259, 2021).
tumor (continued). "Interestingly, those analyses identified c-MYC as a significant upstream regulator and several genes connected to the cellular c-MYC network were hypomethylated in ALK tumor samples." (PMID 33310759, 2021). "In the same study, an alectinib-resistant tumor specimen showed no ALK resistance mutation; however, a PIK3CA G106V mutation was found in this tumor." (PMID 33572278, 2021). "The FISH ALK break-apart positive tumor was found to harbor a novel MYO18A-ALK gene fusion." (PMID 33237469, 2021). "However, some dynamic changes in the tumor-immune microenvironment in response to ALK inhibitors, such as an increase in cells expressing regulatory T cells and programmed death-ligand 1 (PD-L1), have been observed in both the tumor and the stroma." (PMID 34063424, 2021). "The median proportion of positive tumor cells was at least 90% for all four ALK positive cases." (PMID 34173019, 2021). "However, no case has been reported so far in which the SCLC component disappeared after chemotherapy and the tumor responded to ALK-TKI treatment again." (PMID 34401280, 2021). "Furthermore, Western blot analysis of protein lysates prepared from thymic tumours obtained from the CD4/NPM-ALK transgenic mouse line also express BRG1 albeit at a lower level than that observed in ALK+ ALCL cell lines." (PMID 35008316, 2021). "Furthermore, heterogeneous expression of ALK‐protein was seen throughout the entire area of the tumor." (PMID 33565277, 2021). "This suggests that tumor-educated platelets play a key role and could be predictive markers during the treatment of ALK-positive NSCLC." (PMID 34943412, 2021). "It is certainly too premature to assert that liquid biopsies will replace tissue biopsies for the evaluation of the status of ALK at the time of diagnosis and/or on progression of all the mechanisms of resistance of a tumor of a patient treated with TKI that target an ALK rearrangement." (PMID 33467720, 2021). "Immunohistochemical results of these markers associated with tumor stem-like cells and neuroendocrine differentiation suggest that tumor stem cells play a role in the histological transformation and acquired resistance mechanisms of ALK-reposition-positive tumors." (PMID 34660278, 2021). "ALK-directed vaccine in combination with ALK TKI may facilitate tumor cell death and release of tumor neoantigens in order to enhance vaccine-mediated antitumor immune response." (PMID 33806977, 2021). "Here, we investigated whether ALK is phosphorylated in MCC primary tumor samples and nine previously established MCC cell lines, and whether p-ALK status correlates with patient characteristics including MCC-specific and overall survival." (PMID 34029351, 2021). "This study has many issues, but we believe that GKRS is effective for the control of brain metastases because many patients with positive driver gene mutations, especially ALK-positive patients, are expected to survive for a long time after GKRS and have a good prognosis in terms of tumor control." (PMID 35047245, 2021). "Taken together, our findings suggest that the targeting of tumour‐derived S‐type cells could enhance the efficacy of targeted therapeutic drugs in ALK‐positive NB." (PMID 33932101, 2021). "Differential gene expression analysis revealed that ALK tumor cells are characterized by a massive deregulation of gene expression with 2,727 genes significantly down- and 1,618 genes up-regulated as compared with control (Ctrl) cells (FDR-adjusted P < 0.05, log2 fold change > 1)." (PMID 33310759, 2021).